GPC1 (glypican 1)
Diseases named in the same sentence as GPC1 in open-access papers (continued):
Sharing a sentence is not in itself a finding about the gene and the disease.
cancer (continued). "Therefore, more thorough and stringent studies are expected to establish whether GPC-1 in the blood can be a clinical biomarker for certain cancers." (PMID 31355137, 2019). "Previously, we observed that GPC1 may be a specific marker of exosomes in cancer patients." (PMID 29254156, 2017). "Whether GPC1 was a true cancer marker remains to be elucidated." (PMID 29245923, 2017). "All in all, GPC-1 has abstracted more and more attention, and the bioinformatic analysis provide us some meaningful insights of GPC-1 in cancers and some function experiments imply the role of GPC-1 in HCC." (PMID 38982153, 2024). "It has been reported that GPC1 is overexpressed in ESCC and is involved in the development and progression of cancer cells." (PMID 39300946, 2024). "Among the 16 negatively correlated cancers, GPC-1 was highly expressed in HNSC, KIRP, and LIHC, and was low expressed in 7 cancers, including COAD, LUAD, and OV." (PMID 38982153, 2024). "There is accumulating evidence that GPC-1, via upregulation of PI3K/Akt/ERK signaling, plays a crucial role in the progression and chemoresistance in cancer." (PMID 37649964, 2023). "Glypican-1 (GPC1), a membrane-anchored protein, has been reported to be abnormally expressed in various cancers and possibly involved in tumorigenesis; therefore, it is looked upon as a potential clinical biomarker in the blood." (PMID 37304241, 2023). "Taken together these results indicate that suppression of GPC1 expression both with CRISPR/Cas9GPC1 and siRNAGPC1 attenuates progression of T24, U87 and HepG2 cancers by inhibiting cell proliferation." (PMID 36944188, 2023). "A cell surface proteoglycan, glypican-1 (GPC1), is specifically enriched in cancer cell-derived exosome, and it is significantly elevated in PC patients." (PMID 33803470, 2021). "In this study, our aim was to identify whether any member of the glypican family, glypican-1 to glypican-6, has a prognostic impact on the survival of breast cancer patients and could potentially act as therapeutic targets in the battle against the most common cancer in women." (PMID 33742285, 2021). "Later, other surface components (Glypican-1, PD-L1, and CSPG4) were explored as cancer cell ENV markers as well and promising results stimulated further exploration of tumor-derived ENVs as cancer markers." (PMID 34359806, 2021). "The results of RT-PCR indicated that GPC1, STC2, P4HA4, and ENO3 were upregulated in cancer cells while SPAG4 was downregulated in the five cancer cells." (PMID 33747908, 2021). "Here we outlined the remarkable features of HSPGs, such as GPC1, GPC4, GPC5, SDC1, SDC2, SDC3 and HSPG2, and some HSPG-related proteins like heparanase and SULF1/2, in cancer diagnosis." (PMID 34249755, 2021). "Our finding that GPC-1 modulates HS-5 cell contractility is significant as increased contractility of CAFs enables them to form ECM tracks, which are used by cancer cells for collective migration and invasion." (PMID 33927256, 2021). "A panel of four pan-cancer markers (EGFR, EPCAM, HER2, and MUC1) and three putative PC markers (GPC1, WNT2, and GRP94) were investigated individually and together in plasma-derived exosomes." (PMID 33297544, 2020). "The proteoglycan glypican-1 (GPC1) is another molecule, specifically enriched in cancer cell-derived EXOs, that has been assessed as a potential biomarker." (PMID 32443642, 2020). "Our in vitro ADC assay showed that cancer cells highly expressing GPC-1 (namely BxPC-3 and T3M-4) were highly sensitive to GPC-1-ADC, whilst those expressing GPC-1 only at low levels (such as SUIT-2) were comparatively resistant to it." (PMID 32152502, 2020). "The glypican pathway, which was indicated in the KEGG pathway analysis, includes glypican 1 (GPC1, Entry: k08107), which promotes the pathogenesis of many human cancers." (PMID 31311829, 2019).
cancer (continued). "Using mass spectrometry analyses, glypican-1 (GPC1) was identified as a cell surface proteoglycan, which was specifically enriched on cancer-cell-derived exosomes." (PMID 28381299, 2017). "Using mass spectrometry analyses, we identify a cell surface proteoglycan, glypican-1 (GPC1), specifically enriched on cancer-cell-derived exosomes." (PMID 26316886, 2015). "Whilst elevated glypican 1 expression has been documented in different tumors, the downregulation in high-grade tumors observed in this work suggests that this proteoglycan could be involved in cancer development in a more complex and context-dependent manner than previously thought." (PMID 24570896, 2014). "Glypican-1 (GPC-1) overexpression can act as a polyamine transporter, promoting cancer cell proliferation and metastasis, and may influence polyamine uptake." (PMID 40724997, 2025). "Through systematic optimization of the immobilization of antibody molecules and the anti‐fouling strategy of the sensing interface, the sensing platform demonstrates the capability to detect trace amounts of cancer markers, such as MIF, EGFR, and GPC1, within intricate biological media." (PMID 40598854, 2025). "There is compelling evidence that Glypican-1 (GPC-1), a cell surface antigen overexpressed in various solid tumors but largely absent in normal tissues, plays a key role in the progression of cancers such as prostate, pancreatic, bladder, gastroesophageal, ovarian, and GBM." (PMID 40867331, 2025). "In addition, GPC-1 expression was upregulated in ACC, ESCA, HNSC, and THCA from stage I to stage II with the progression of cancer stage, except in KIRC (P < 0.05)." (PMID 38982153, 2024). "In this regard, GPC1 which was identified in many studies identified as cancer exosomes specific marker, was not identified here as many of datasets did not pick up this protein in analysis." (PMID 38529947, 2024). "Based on the analysis of multiple databases, our study found that GPC-1 was upregulated in CHOL, DLBC, and other 10 common cancers and downregulated in 10 cancers, suggesting that GPC-1 may have different functions in different types of cancer." (PMID 38982153, 2024). "Here, a cancer-wide GPC expression study, using clinical cancer patient data in The Cancer Genome Atlas, reveals net upregulation of GPC1 and GPC2 in primary solid tumors, whereas GPC3, GPC5 and GPC6 display lowered expression pattern compared to normal tissues." (PMID 36944188, 2023). "Glypican proteoglycan (GPC1 and GPC6), core membrane-anchored heparan sulfate proteoglycans, were upregulated in ESCC tissues compared with para-carcinoma tissues, whereas syndecan proteoglycans (SDC1, SDC2, and SDC4), transmembrane heparan sulfate proteoglycans, were downregulated." (PMID 35840985, 2022). "Therefore, we differentiated PDEs from TEVs using the candidate cancer surface markers ITGA2, ITGAV, and GPC1." (PMID 34948417, 2021). "GPC1-subtype tumors displayed distinct Warburg-like proteomic features, with increased LDHA, PKM2, and HK2 expression that facilitates lactate production and confers resistance to hypoxic stress in cancer cells." (PMID 32620753, 2020). "In Proteoglycans in cancer pathway, FZD9, GPC1, PAK1, FZD1, and ACTB were extracted." (PMID 30733969, 2019). "However, inhibition of GPC-1 expression also led to a slight increase in the expression of GPC-5, which can also contribute to cancer progression." (PMID 31391540, 2019). "Therefore, it is desirable to design a simple detection method of GPC-1 providing a useful tool for the assessment of the level of GPC-1 and its effect in cancers and neuro-degenerative disorders." (PMID 30202003, 2018). "We have developed such a test (manuscripted accepted) and are currently investigating the ability of soluble GPC-1 in blood to distinguish aggressive from non-aggressive cancer." (PMID 29672570, 2018). "Recently, GPC1 and GPC3 were found to be predictor and target for some cancers, including PC." (PMID 24736782, 2014).
cancer (continued). "GPC1, as well as glypican-1, is specifically enriched on cancer-cell-derived exosomes and may serve as a potential non-invasive diagnostic and screening tool to detect early stages of pancreatic cancer." (PMID 38365849, 2024). "Even though the finding showed that GPC-1 expression was correlated with some related genes in HCC, we were unsure whether GPC-1 interacts with these genes to be involved in the occurrence and development of cancer." (PMID 38982153, 2024). "Thus, despite being considered as a potential target for cancer therapy in some solid tumors, the actual application of targeting GPC1 has not been realized." (PMID 37775746, 2023). "Based on these encouraging reports we hypothesize that targeting GPC-1 alone or in combination with PI3K inhibitors may offer an attractive alternative strategy to improve drug sensitivity and overcome drug resistance in refractory cancers such as EAC." (PMID 37649964, 2023). "Furthermore, a multiparametric exosome profiling was also developed and conducted by screening exosomes from patient plasma with a combination of ten surface markers including four biomarkers from a major group of cancers, three putative PDAC markers including GPC-1, and three pan-exosome markers." (PMID 35757760, 2022). "However, our data also show that GPC1 was expressed from low-grade precancerous lesions of the pancreas, which did not always develop into carcinoma." (PMID 29245923, 2017). "Compared with GPC-1, GPC-2, GPC-3, and GPC-5, few studies have investigated the mechanism and prognostic significance of GPC-4 and GPC-6 expressions at the mRNA level in malignant tumors, and no related reports have been found in HCC." (PMID 33902495, 2021). "Measurement of GPC-1 expression levels, rather than GPC-1 positivity per se, may be a means of distinguishing between aggressive and non-aggressive cancer." (PMID 29672570, 2018).
adenocarcinoma (3 papers, 2020 to 2025). A common cancer characterized by the presence of malignant glandular cells. "Killing of the GPC-1 high expressing DU-145 cell line, closest to adenocarcinoma, was compared to killing of the PC3 cell line, which expresses moderate levels of GPC-1 (20,268 molecules/cell)." (PMID 33302918, 2020).
cardiovascular disease (3 papers, 2021 to 2025). "Comparative transcriptomic analysis revealed that genes related to cardiovascular disease (e.g., Sgcb, Adcy2, Itga1, Itgb8, Ifng, and Gpc1) were upregulated in the livers of R. pruinosus compared to carnivorous and omnivorous rodents, indicating a higher cardiovascular disease risk." (PMID 40941321, 2025). "Among the glycocalyx components, glypican 1, which acts through eNOS-dependent mechanisms, has recently emerged as a player in cardiovascular diseases." (PMID 37834029, 2023).
infection (3 papers, 2019 to 2025). The state of being infected such as from the introduction of a foreign agent such as serum, vaccine, antigenic substance or organism. "The drug also inhibited infection of the respective control cells, although infection of the controls was less than GPC1 overexpressing or alkyl-CIMSS-treated cells." (PMID 41278678, 2025). "Further, increased infection by either alkyl-CIMSS or genetic manipulation of GPC1 could be reduced by chemical inhibition of TGF-β signaling." (PMID 41278678, 2025). "However, infection remained less in the alkyl-CIMSS treated KO compared to control cells, indicating that the increase in GPC1 only partially overcame the absence of TMEM16F." (PMID 41278678, 2025).
GPC1 also shares sentences with these, for which no sentence is quoted: metastatic tumors (5 papers); cervical cancer (3); mesothelioma (3); benign prostatic hyperplasia (2); cholangiocarcinoma (2); lung (2); rhabdomyosarcoma (2); ameloblastoma (1); behavioral disorders (1); benign breast disease (1); benign tumors (1); bile duct cancer (1); bladder urothelial carcinoma (1); brachydactyly (1); brain glioma (1); carcinoma in situ (1); Cognitive impairment (1); colorectal adenocarcinoma (1); Crohn disease (1); edema (1); endometrial carcinoma (1); endotoxemia (1); epithelioid mesothelioma (1); esophageal adenocarcinoma (1); gallbladder carcinoma (1); head and neck cancer (1); head and neck squamous cell carcinoma (1); invasive carcinoma (1); malignant glioma (1); metastatic colorectal cancer (1).
A further 18 diseases each share a sentence with GPC1 in 1 paper.